MIR8087 (microRNA 8087)
Synonyms: hsa-mir-8087
Gene: MicroRNA gene on chromosome 11 (27,514,970 to 27,515,047, reverse strand). Ensembl gene ENSG00000278483.
Homologues: Orthologues: chimpanzee MIR8087 (100% identical).